ZBTB25 (zinc finger and BTB domain containing 25)
Description:
May be involved in transcriptional regulation.
Synonyms: C14orf51; KUP; ZNF46
Tractability: PROTAC: UniProt records ubiquitination sites on it; ubiquitination databases record sites on it.
Gene: Protein-coding gene on chromosome 14 (64,449,106 to 64,505,232, reverse strand). Ensembl gene ENSG00000089775.
Subcellular location: Nucleus
Subcellular location (Human Protein Atlas): Nucleoplasm
Gene Ontology:
Molecular function: protein binding; DNA-binding transcription factor activity; DNA-binding transcription repressor activity, RNA polymerase II-specific; RNA polymerase II cis-regulatory region sequence-specific DNA binding
Biological process: negative regulation of transcription by RNA polymerase II; regulation of cytokine production; regulation of immune system process
Cellular component: nucleoplasm; nucleus
Genetic constraint (gnomAD): Loss-of-function variants: 20 observed, 35.8 expected, observed/expected ratio (o/e) 0.56, 90% interval 0.39 to 0.81. The upper end of that interval is the gene's LOEUF score, 0.81, which puts it in group 3 of 6, group 1 being the genes least tolerant of losing a copy. Missense variants: 437 observed, 547.52 expected, observed/expected ratio (o/e) 0.8, 90% interval 0.74 to 0.86. Synonymous variants: 175 observed, 196.68 expected, observed/expected ratio (o/e) 0.89, 90% interval 0.79 to 1.01.
Homologues: Orthologues: chimpanzee ZBTB25 (99% identical), macaque ZBTB25 (97% identical), pig ZBTB25 (95% identical), dog ZBTB25 (94% identical), mouse Zbtb25 (92% identical), rat Zbtb25 (90% identical), guinea pig ZBTB25 (88% identical), rabbit ZBTB25 (74% identical), tropical clawed frog zbtb25 (58% identical), zebrafish zbtb25 (41% identical). Paralogues in human: ZBTB49 (19% identical), ZBTB14 (18% identical), BCL6 (17% identical), ZBTB21 (17% identical), BCL6B (15% identical), ZBTB7B (15% identical), ZBTB46 (15% identical), NACC2 (14% identical), NACC1 (14% identical), ZBTB3 (14% identical), ZBTB33 (13% identical), ZBTB6 (13% identical), and 16 more.
Diseases named in the same sentence as ZBTB25 in open-access papers:
ZBTB25 is named in the same sentence as 5 diseases in open-access papers, as found by Europe PMC text mining. Sharing a sentence is not in itself a finding about the gene and the disease. The quoted sentences say what the papers report.
lung adenocarcinoma (1 paper, 2021). A carcinoma that arises from the lung and is characterized by the presence of malignant glandular epithelial cells. "In human lung adenocarcinoma epithelial cells infected with influenza virus, ZBTB25 was found to interact with the viral RNA-dependent RNA polymerase (RdRp) and to enhance its transcription." (PMID 33627504, 2021).
infection (3 papers, 2016 to 2023). The state of being infected such as from the introduction of a foreign agent such as serum, vaccine, antigenic substance or organism. "WT and ZBTB25 KO cells were inoculated with OC43 at 0.03 multiplicity of infection (MOI) for a brief period, and then cells were gently washed and allowed to produce new virus." (PMID 37890782, 2023). "Naïve cells treated with supernatant from ZBTB25 KO cells showed a higher proportion of infection at more dilute conditions than naïve cells treated with supernatant from WT cells." (PMID 37890782, 2023). "This is particularly clear around a dilution factor of log3, where approximately 20% of cells treated with WT supernatant were infected, compared with 60% infection in cells treated with ZBTB25 KO supernatant." (PMID 37890782, 2023). "Following infection, ZBTB25 and Sin3a were found to be recruited to the IL-12B promoter at 24 hpi." (PMID 33627504, 2021).
tumor (1 paper, 2021). "ZBTB25 is a transcriptional repressor, and the exact physiological function of the ZBTB family is not well understood; a few ZBTB proteins have been reported to participate in tumor progression and chromatin remodeling and have a repressive role in the differentiation and activation of T cells." (PMID 33627504, 2021).
ZBTB25 also shares sentences with these, for which no sentence is quoted: diabetes (1 paper); tuberculosis (1).